MYBL2 (MYB proto-oncogene like 2)
Diseases named in the same sentence as MYBL2 in open-access papers (continued):
Sharing a sentence is not in itself a finding about the gene and the disease.
prostate carcinoma (21 papers, 2007 to 2025). A carcinoma that arises from epithelial cells of the prostate gland. "Our findings demonstrate that the overexpression of the MYBL2 molecule is significantly associated with the progression of bone metastasis in prostate cancer." (PMID 40092688, 2025). "MYBL2 upregulation has also been linked with prostate cancer aggressiveness and resistance to AR targeting and appears to be a key target of the histone demethylase KDM5B58." (PMID 40624104, 2025). "Nevertheless, the oncogenic role and underlying mechanisms of MYBL2 in bone metastasis of prostate cancer (PCa) have yet to be elucidated." (PMID 40092688, 2025). "MYBL2 has been implicated in promoting tumor progression by regulating the cell cycle in various cancers, including gastric cancer, prostate cancer, and also liver cancer." (PMID 38255993, 2024). "It has been previously reported that higher levels of MYBL2 are associated with poor prognosis in both hematological and solid tumors including prostate cancer." (PMID 36087093, 2022). "A new DNA methylation 10-CPG disease-free survival prognosis shows that MYBL2 is associated with a high risk of prostate cancer." (PMID 35664326, 2022). "Of note, multiple genes hitherto known to be associated with prostate cancer progression were observed in the top list of upregulated entities including but not limited to MYBL2, ESM1, PBK, and UBE2C in PC3, and MMP1, CCL5, and STC1 in DU145." (PMID 31493351, 2019). "Therefore, this study aimed to elucidate the role and underlying mechanisms of MYBL2 in facilitating bone metastasis in prostate cancer." (PMID 40092688, 2025). "Given the role of MYBL2 in proliferation, we asked whether the loss of Mybl2 impaired the growth of NE-like murine prostate cancer cells." (PMID 39113611, 2024). "Moreover, loss of Mybl2 decreased signaling pathways related to pluripotency and proliferation highlighting the important role that MYBL2 plays in orchestrating prostate cancer cell stemness." (PMID 39113611, 2024). "Genetic inhibition of Mybl2 using independent murine prostate cancer cell lines representing phenotypic plasticity demonstrated Mybl2 loss significantly decreased in vivo growth as well as cell fitness and repressed gene expression signatures involved in pluripotency and stemness." (PMID 39113611, 2024). "MYBL2 overexpression has been shown to inhibit Hippo signaling by regulating expression of RACGAP1 leading to activation of YAP signaling in prostate cancer." (PMID 40115748, 2025). "In order to examine the impact of MYBL2 on tumor growth and metastasis in prostate cancer (PCa) in vivo, RM1-luc cells were administered into the tibial plateau region of C57BL/6 mice to establish a PCa xenograft metastasis model." (PMID 40092688, 2025). "MYBL2 has been shown to be important factor in prostate cancer progression as a very recent study introduces it as a driver of prostate cancer plasticity, while an earlier study reported that MYBL2 is upregulated in castration-resistant prostate cancer (CRPC)." (PMID 40115748, 2025). "This study provides robust evidence linking MYBL2 to poor prognosis in patients with prostate cancer (PCa), predominantly by promoting invasion and epithelial-mesenchymal transition (EMT)." (PMID 40092688, 2025). "MYB proto-oncogene like 2 (MYBL2) is a key regulator of prostate cancer (PCa) progression and bone metastasis." (PMID 40342734, 2025). "Together, this work demonstrates MYBL2 as an important MR-TF driving phenotypic plasticity in prostate cancer." (PMID 39113611, 2024). "Together, these data indicate that CDK2 inhibition represents a novel therapeutic approach to treat prostate cancers progressing on AR signaling inhibition and exhibiting phenotypic plasticity that includes increased expression and function of MYBL2." (PMID 39113611, 2024).
prostate carcinoma (continued). "Although MYBL2 is implicated in CRPC-Ad growth, no studies have examined the specific functional and clinical implications of increased MYBL2 expression in driving phenotypic plasticity in prostate cancer." (PMID 39113611, 2024). "MYBL2 impairs the Hippo signaling pathway and regulates castration resistance and metastasis in prostate cancer." (PMID 37684641, 2023). "We found that the MYBL2 gene was indeed transcriptionally activated by KLF5K369Q in prostate cancer cells." (PMID 36810084, 2023). "One such change was the upregulation of MYBL2, which functionally promotes bone metastasis in prostate cancer." (PMID 36810084, 2023). "Two KLF5K369Q-upregulated and NTZ-downregulated genes, MYBL2 and TIMM8A, were upregulated in human prostate cancer, and the upregulation was associated with worse patient survival." (PMID 36810084, 2023). "In addition, targeting MYBL2 blocks bone metastasis in prostate cancer cells, and higher MYBL2 expression levels are associated with higher tumor stage, higher tumor grade, higher risk of metastatic relapse, and worse prognosis in patients with prostate cancer." (PMID 36810084, 2023). "Assessments of the baseline protein expression levels of KDM5D and MYBL2 in a panel of prostate cancer cell lines revealed the two cell lines with detectable KDM5D, LNCaP, and CWR22Rv1, had the lowest MYBL2 expression." (PMID 36087093, 2022). "Higher levels of the transcription factor MYBL2 increase the aggressiveness and decrease the sensitivity of hormone‐sensitive prostate cancer to androgen deprivation and docetaxel." (PMID 36087093, 2022). "The clinical relevance of elevation of MYBL2 in prostate cancer was seen by the fact that patients with higher MYBL2 had a higher rate of relapse after treatment of localized disease." (PMID 36087093, 2022). "The transcription factor MYBL2 impacts both in vitro hormone‐sensitive prostate cancer sensitivity to androgen deprivation and taxanes and lower levels are associated with better clinical outcomes in men with hormone‐sensitive prostate cancer." (PMID 36087093, 2022). "For instance, MYBL2 was overexpressed in castration-resistant prostate cancer and promoted cell growth and metastatic by promoting YAP1 transcriptional activity." (PMID 34568071, 2021). "These insights may inform the future development of targeted therapies against MYBL2 for the treatment of bone metastases in prostate cancer." (PMID 40092688, 2025). "More comprehensive studies are needed to confirm whether potential FOXM1/MYBL2/YAP pathway is responsible for regulating AR activity in response to changes in ECM stiffness in prostate cancer." (PMID 40115748, 2025). "Furthermore, high MYBL2 activity identifies prostate cancer that would be responsive to CDK2 inhibition." (PMID 39113611, 2024). "In the present study, using genetically engineered mouse models (GEMM) and human gene expression data, we demonstrate the enrichment of MYBL2 expression and function in prostate cancers displaying phenotypic plasticity when compared with their adenocarcinoma counterparts." (PMID 39113611, 2024). "Given the role of MYBL2 in proliferation, genome stability, and reprograming, we sought to understand cellular consequences when Mybl2 expression was lost in murine prostate cancer cell lines." (PMID 39113611, 2024). "MYBL2 was recently demonstrated to promote metastasis and castration resistance of prostate cancer." (PMID 36810084, 2023). "In advanced prostate cancer, MYBL2 expression positively correlates with metastasis." (PMID 31756170, 2019). "Therefore, we used an established MYBL2 gene signature to identify and nominate candidate drug targets as a novel therapeutic direction using the cancer therapeutics response portal for patients with prostate cancer with overexpression of MYBL2 and/or increased MYBL2 activity." (PMID 39113611, 2024).
prostate carcinoma (continued). "Our study identifies MYBL2 as a MR-TF in phenotypic plastic prostate cancer and implicates CDK2 inhibition as a novel therapeutic target for this most lethal subtype of prostate cancer." (PMID 39113611, 2024). "Looking over the spectrum of disease progression in human prostate cancer samples, tumors from patients with NEPC represented the most enriched sample set for increased MYBL2 expression." (PMID 39113611, 2024). "In the GSE21034 dataset, expression levels of both MYBL2 and TIMM8A were available in primary tumors, visceral metastases, and bone metastases of prostate cancer." (PMID 36810084, 2023). "Among the 7 KLF5K369Q-regulated and NTZ-responsive genes, the MYBL2 (Myb-related protein B) is particularly interesting, as a previous study has demonstrated that MYBL2 promotes castration-resistant growth and bone metastasis of prostate cancer." (PMID 36810084, 2023). "For example, two Ac-KLF5-upregulated and NTZ-downregulated genes, MYBL2 and TIMM8A, were upregulated in human prostate cancer." (PMID 36810084, 2023). "Furthermore, knockdown of MYBL2 significantly inhibited the proliferation of prostate cancer cell lines in the absence of androgens." (PMID 39113611, 2024). "MYBL2 is currently not druggable, so using a MYBL2 gene signature, we identified CDK2 as a potential therapeutic target for phenotypic plastic prostate cancer." (PMID 39113611, 2024).
cervical carcinoma (15 papers, 2013 to 2025). A carcinoma arising from either the exocervical squamous epithelium or the endocervical glandular epithelium. "MYBL2 was identified as a key hub gene in a bioinformatic screening study aimed at discovering novel biomarkers for cervical cancer." (PMID 40508156, 2025). "To date, the functionality of circ-MYBL2 has only been investigated in two types of cancer including cervical cancer and multiple myeloma, while the roles of circ-MYBL2 in these two types of cancer are opposite." (PMID 35387554, 2022). "Cervical cancer tissues exhibited increased expression levels of circ-MYBL2 and overexpression of circ-MYBL2 increased cell invasion and proliferation by sponging miR-361-3p." (PMID 35387554, 2022). "Previous studies have also indicated that MYBL2 mRNA is overexpressed in cervical cancer using gene expression profiling and TaqMan PCR." (PMID 35664780, 2022). "Recently, it has been reported that MYBL2 is a novel candidate biomarker gene for various cancer cells such as colorectal, gallbladder and cervical cancer." (PMID 32742192, 2020). "In cervical carcinoma cells, miR-29 and miR-30 regulate the expression of MYBL2 by binding to its 3’UTR, and these miRNAs can inhibit cellular DNA synthesis and play essential roles in Rb-driven cellular senescence." (PMID 30305611, 2018). "However, circ-MYBL2, a circular RNA spliced from the exons of the MYBL2 gene, highly expressed in cervical cancer cells, can act as a sponge for miR-665 and lift its inhibitory effect." (PMID 37894282, 2023). "Moreover, downregulation of MYBL2 with siRNA silencing leads to increased senescence in primary human foreskin fibroblasts and HeLa cervical cancer cells." (PMID 28286417, 2017). "In addition, miR-30 family members have been shown to be important for inducing cellular senescence by targeting the oncogenic transcription factor MYBL2 in cervical carcinoma cell lines." (PMID 24257477, 2013).
gastric cancer (15 papers, 2015 to 2026). A primary or metastatic malignant neoplasm involving the stomach. "The oncogenic effects of E2F family genes (E2F1 and E2F7) in gastric cancer were at least partially mediated through transcriptional activation of MYBL2." (PMID 41491570, 2026). "Within gastric cancer, MYBL2 modulates DNA damage via UBEC2 activation, thereby promoting tumor progression and resistance to cisplatin therapy." (PMID 38994352, 2024). "Vorinostat induced apoptosis in U937 cells by downregulation of MYB and MYBL2, and cell death upon MYB suppression in gastric cancer cells." (PMID 38835346, 2024). "In our study, we found that MYBL2 could be positively regulated by PDFN2, thus promoting gastric cancer cell cycle progression." (PMID 37538116, 2023). "Transcription factors MYB, MYBL2, ETV4, LEF1,TFAP2A were up-regulated in gastric cancer tissues." (PMID 25860484, 2015). "Specifically, five transcription factors MYB, MYBL2, ETV4, LEF1 and TFAP2A were up-regulated and they formed the TF-gene regulatory networks with 41 genes, 38 of which were up-regulated and 3 were down-regulated in gastric cancer tissues." (PMID 25860484, 2015).
neuroblastoma (15 papers, 2010 to 2024). Neuroblastoma (NB) is the most common solid, extracranial childhood tumor. "Since MYBL2 expression in neuroblastoma is associated with poor prognosis, citalopram has the potential to become a drug candidate for patients with MYBL2-driven neuroblastoma." (PMID 38835346, 2024). "The antidepressant citalopram exhibited cytotoxic activity and strongly suppressed MYBL2 in neuroblastoma cells (B104, SH-SY5Y, and Kelly)." (PMID 38835346, 2024). "In contrast, MYBL2 activity was upregulated via cyclin D1 suppression in neuroblastoma cells upon treatment with RA, which led to RA-mediated cell differentiation." (PMID 38835346, 2024). "In neuroblastoma, MYBL2 directly regulates expression of ApolipoproteinJ/Clusterin and thereby mediates resistance to apoptosis induced by doxorubicin." (PMID 28640249, 2017). "ZNF622 (zinc finger protein 622), also known as ZPR9 (zinc finger protein 9), enhances the transcriptional activity of the MYBL2 (also known as B-MYB) transcription factor to regulate cellular growth of neuroblastoma cells, but may also have cytoplasmic roles in the regulation of apoptosis." (PMID 34283051, 2021). "Citalopram drastically decreased the expression of MYBL2, BIRC5 and BARD1 poor prognosis factors of neuroblastoma with fold-changes of -107 (p<2.26 10−7), -24.1 (p<5.6 10−9) and -17.7 (p<1.2 10−7)." (PMID 28467792, 2017). "We specifically studied MYCN, MYBL2, BIRC5, BARD1 and AURKA, poor prognosis markers of neuroblastoma, and CCNA2 and CCNE1 genes, involved in general carcinogenesis." (PMID 28467792, 2017). "The alkaloids camptothecin and topotecan, which reportedly interacted with G-quadruplex regions of the MYB promoter and led to MYB suppression, also suppressed MYBL2 and MYCN expression in IMR-32, Kelly, and LAN-5 neuroblastoma cells accompanied by apoptosis induction." (PMID 38835346, 2024). "Last, our study defined for the first time through a cross-species integrative transcriptomics approach putative master regulators for MYCN-driven neuroblastoma tumor development and revealed FOXM1 and the DREAM complex members MYBL2 and E2F8 as top-scoring candidates." (PMID 34638267, 2021). "Interestingly, the expression of 3 of these genes i.e. MELK, MYBL2 and PLK1 is remarkably highly correlated with FOXM1 expression levels in 200 neuroblastoma tumors (correlation coefficients >0.9) suggesting a very tight co-regulated transcriptional control." (PMID 30504901, 2018). "The loop involving MYBL2 and MYCN might constitute a therapeutic target particularly for the 20% of aggressive neuroblastomas where amplification of MYCN is observed." (PMID 28467792, 2017). "Similarly to MYBL2, MYB expression is significantly increased in MYCN-amplified neuroblastomas predicting poor survival." (PMID 25477524, 2015).
colon cancer (13 papers, 2008 to 2025). "Ren used siRNA to interfere with the expression of MYBL2 in colon cancer, and the proliferation of tumor cells was decreased." (PMID 35664780, 2022). "We also checked the correlation between ETV5 and colon cancer cell proliferating markers (MK167, MYC, MYBL2) in order to assess the effect of ETV5 over cell proliferation." (PMID 33658938, 2020).
leukemia (9 papers, 2017 to 2024). A malignant (clonal) hematologic disorder, involving hematopoietic stem cells and characterized by the presence of primitive or atypical myeloid or lymphoid cells in the bone marrow and the blood. "For example, it has conclusively been shown that circMYBL2, derived from AML-related gene MYBL2, exerts a cancerogenic role in leukemia harboring FLT3-ITD mutation." (PMID 36058922, 2022). "Although MYBL2 had been validated to participate in multiple cancers including leukemia, the role of MYBL2 polymorphisms in acute lymphoblastic leukemia (ALL) was still not clear." (PMID 34568071, 2021). "Circ-MYBL2 knockdown in leukemia cells harboring the FLT3-ITD mutation increased the number of cells in Sub-G1 and G0/G1 phases and decreased ones in S and G2/M phases, thus substantially impairing the proliferation of these cells, whereas it merely affected the FLT3-nonmutant cells." (PMID 37124518, 2023). "For example, circMYBL2, produced from MYBL2, which was reported to be linked to leukemia, could promote the advancement of FLT3-ITD-mutant acute myeloid leukemia." (PMID 36058922, 2022). "Molecular function analysis showed that LEE011 induced senescence in leukemia cells partially through downregulation of the transcriptional expression of MYBL2." (PMID 28286417, 2017). "A loss of circ-MYBL2 in mutant cells resulted in a decline in FLT3 phosphorylated kinases and impairment of STAT5 phosphorylation, a key downstream protein of oncogenic FLT3 and crucial for aberrant leukemia cell growth." (PMID 37124518, 2023). "MYBL2 (MYB proto-oncogene like 2), also known as B-MYB, belongs to the MYB family of transcription factor which was first identified as a vertebrate homolog of the v-myb oncogene causing leukemia in chickens." (PMID 34568071, 2021). "The MYBL2 gene, which is also known as B-MYB, is a member of the myeloblastosis family of transcription factors, first identified as cellular homologues of the v-myb oncogene that is known to cause leukemia in chickens." (PMID 28784180, 2017). "Circ-MYBL2 promotes proliferation and cell-cycle progression and inhibits apoptosis of FLT3-ITD+ leukemia cells." (PMID 37124518, 2023). "In addition, in a leukemia model in which myelodysplastic syndrome mice were used, MYBL2 (MYB proto-oncogene like 2) knockdown also resulted in decreased UBE2C expression." (PMID 29596365, 2018).
liver cancer (9 papers, 2019 to 2024). An epithelial or non-epithelial malignant neoplasm that arises from the liver. "Our study on liver cancer also proved that MYBL2 is highly expressed in cancer tissues, and the high-expression group has a poor prognosis (P=0.00047)." (PMID 36685007, 2023). "Among the seven important DEGs, MAFG-DT (logFC = 2.295817), GPRIN1 (logFC = 2.444281), and MYBL2 (logFC = 3.861042) were all significantly elevated in liver cancer samples." (PMID 36685007, 2023). "MYBL2 transfection in HepG2 and Huh7 liver cancer cells enhanced the proliferation and G1/S and G2/M cell cycle phase transition, while the opposite occurred when MYBL2 expression was inhibited by specific siRNA." (PMID 31569678, 2019). "The transfection of Huh7 liver cancer cell line with MYBL2 strongly stimulates the G1-S and G2-M phases of cell cycle, while the contrary follows MYBL2 silencing." (PMID 31569678, 2019). "MYBL2 transfection in Huh7 liver cancer cells activated genes involved in cell proliferation, such as MDK (Midkine), an activator of AKT and ERK1/2 pathways." (PMID 31569678, 2019). "The expression levels of MYBL2, SPP1, CTSV and EPO were remarkably increased in liver cancer cells compared with normal liver cells, while the expression level of CYP2C9 was significantly decreased (p < 0.05)." (PMID 36650832, 2023). "To understand the role of MYBL2 in HCC, we looked into the liver cancer cohort of the TCGA database." (PMID 36494680, 2022). "Further, ChIP–PCR experiments demonstrated that MYBL2 was physically recruited to the RRM2 promoter on the site 2 in CRC cells, similar to the ChIP-Seq data of MYBL2 in the liver cancer HepG2 cells." (PMID 34234118, 2021).